ALB (albumin)
Diseases named in the same sentence as ALB in open-access papers (continued):
Sharing a sentence is not in itself a finding about the gene and the disease.
Hypertension (continued). "Anxiety state, BMI, hypertension, preoperative blood lipid levels, and albumin level on the third day after surgery were related to the occurrence of DGE after PPPD." (PMID 40988445, 2025). "While hypertension (OR = 5.747, 95% CI: 1.186–27.862, p = 0.030) and elevated platelet-to-albumin ratio (PAR) (OR = 1.256, 95% CI: 1.025–1.540, p = 0.028) were identified as independent risk factors for autonomic dysfunction based on the CARTs results." (PMID 40092067, 2025). "Numerous dysregulated proteins were identified in the uEVs of patients with hypertension with an albumin creatinine ratio (ACR) <10 mg/g versus those of patients with hypertension with an ACR of 10–30 mg/g, i.e. in the upper normal range." (PMID 40873806, 2025). "Concerning albumin levels, those with low levels (<3.5 g/dL) were more likely to be older (39.5% aged ≥70), female (64.3%), have hypertension (58.2%), and have bleeding disorders (9.2%) compared to those with normal levels (≥3.5 g/dL)." (PMID 41527604, 2025). "Significant differences were found in white blood cell (WBC) count, platelet count, AST, ALT, bilirubin, albumin, hemoglobin, the rate of hypertension, and serum let7b/c/g expression between the two groups." (PMID 40156487, 2025). "This study examined the ratio of erythrocyte distribution width (RDW) to albumin concentration (RAR) and all-cause, cardiovascular disease (CVD), and cancer mortality in the hypertension population, focusing on the role of inflammatory markers as mediators." (PMID 40408377, 2025). "The naïve Bayes model incorporated HDL-C, ALB, DM, total bilirubin, creatinine, hypertension, TC, fasting insulin, age, PLT, height, sex, BMI, uric acid, ALT, TG, body weight, HbA1c, LDL-C, and AST." (PMID 40361915, 2025). "Current therapies mainly focus on glycemic control, hypertension management, and albumin reduction to mitigate kidney damage." (PMID 41019174, 2025). "These variables, namely age, stroke, hypertension, triiodothyronine, albumin globulin ratio, and homocysteine, were used to develop a predictive nomogram." (PMID 41311702, 2025). "The seven-year follow-up revealed hypertension development in 37.4% of participants and urinary albumin excretion in 18.0%." (PMID 39897307, 2025). "The univariate and multivariate analyses revealed that hypertension, CHF, Cor pulmonale, low DBP, elevated WBC count, neutrophil ratio, serum creatinine, CRP, and PCT, decreased albumin and platelets were associated with adverse outcomes." (PMID 41179861, 2025). "The disparities observed between various studies on serum albumin, uric acid, and hypertension can be attributed to multiple complex factors that interplay in clinical research." (PMID 39897307, 2025). "The results revealed a statistically significant interaction with gender, hypertension, cerebrovascular disease, stroke, and albumin levels (all interaction P values < 0.05)." (PMID 40660150, 2025). "Our findings linking respiratory failure history, hypertension, albumin, lymphocyte levels, and clinical deterioration of COPD occurrence align with existing literature." (PMID 40028201, 2025). "In the MLP model, the final features were body weight, uric acid, PLT, BMI, ALT, hypertension, fasting insulin, ALB, DM, LDL-C, AST, creatinine, height, age, HDL-C, HbA1c, total bilirubin, TG, TC, and sex." (PMID 40361915, 2025). "Hypertension (12.5%), Thrombocytopenia (12.5%) and Albumin decreased (7.5%) were the most frequently observed grade 3-4 TRAEs.No treatment-related mortality occurred during the study period." (PMID 40821815, 2025). "Individuals with elevated HbA1c levels were more likely to be non–Hispanic Black, and were associated with lower BMI, former smoking, hypertension, higher eGFR categories, reduced physical activity, lower NLR, and decreased albumin and hemoglobin levels." (PMID 40007805, 2025).
Hypertension (continued). "Regular monitoring is recommended for these family members, and special attention should be given to subsequent follow‐ups for the emergence of hypertension, increased urinary albumin and red blood cell counts, renal failure, and damage to the eyes and ears." (PMID 39924725, 2025). "Hypertension can lead to endothelial dysfunction and increased vascular permeability, potentially contributing to albumin leakage." (PMID 40687754, 2025). "The univariate logistic regression analysis showed that the POD incidence was positively correlated with being male, polypharmacy, hypertension, hemoglobin, albumin, and C-reactive protein (p-value < 0.1)." (PMID 40005452, 2025). "In the KNN model, the final features included PLT, uric acid, ALT, body weight, creatinine, fasting insulin, AST, age, height, BMI, total bilirubin, HDL-C, triglycerides (TG), LDL-C, sex, DM, hypertension, ALB, TC, and HbA1c." (PMID 40361915, 2025). "Although, in our study, hypertension (P=0.879), nephrotic range proteinuria (P=0.467), serum albumin levels (P=0.502), CRP (P=0.099), and reduced C3 level (P=0.453) were not considered as factors predicting RPGN." (PMID 41246678, 2025). "In secondary prevention, this understanding broadens therapeutic options by incorporating uric acid-lowering and albumin-elevating agents into conventional hypertension management protocols." (PMID 39897307, 2025). "Clinical studies done in countries like Bangladesh, China, Korea, and Japan concluded that patients with elevated uric acid levels and decreased albumin levels had a high chance of developing hypertension." (PMID 39897307, 2025). "Hypertension, defined as office systolic blood pressure of ≥140 mmHg or diastolic blood pressure of ≥90 mmHg and albuminuria, was defined as a sex-based albumin–creatinine ratio (ACR) of >355 mg/g for females and >250 mg/g for males." (PMID 41302171, 2025). "Increased ORs for high albumin levels were observed in current drinking, hypertension, dyslipidemia, history of fatty liver, whereas decreased ORs were observed for men." (PMID 41248155, 2025). "Hypertension, serum albumin, baseline creatinine and baseline cystatin C were significant predictors of renal recovery in the studied patients (p = 0.017, 0.006, 0.030, and < 0.001, respectively)." (PMID 40707908, 2025). "The three most critical predictors were a history of hypertension, serum albumin level, and TCV, followed by age, creatinine level, admission blood glucose level, platelet count, NIHSS score, neutrophil-to-lymphocyte ratio, and onset-to-admission time." (PMID 40852520, 2025). "Before PSM, significant differences were observed in several baseline characteristics, including preoperative BMI, hypertension status, preoperative total protein and albumin levels, and tumor differentiation (p < 0.05)." (PMID 40960020, 2025). "The occurrence of anastomotic leakage after esophageal cancer surgery is related to various factors, including BMI, hypertension, chronic bronchitis, peptic ulcer, operation way, anastomotic way, postoperative albumin, and anastomotic location." (PMID 40956011, 2025). "Higher cancer incidence was noted among non‐Hispanic whites, those with an education level of high school or above, married or cohabiting individuals, alcohol consumers, PIR > 1, and those with hypertension, hyperlipidemia, low albumin levels, and higher NPAR." (PMID 39831739, 2025). "The top three predictors were a history of hypertension, serum albumin level, and total calcified volume." (PMID 40852520, 2025). "Through network analysis we observed that CNFL has multivariate interactions with common carotid artery (CCA IMT, CCA RI, CCA PSV), age, arterial hypertension, albumin/creatinine ratio and, unsurprisingly, other microscopic nerve measurements." (PMID 41375715, 2025).
Hypertension (continued). "The model, incorporating key factors such as age, stroke history, hypertension, triiodothyronine levels, albumin-globulin ratio, and homocysteine levels, demonstrated robust performance in assessing WMH risk." (PMID 41311702, 2025). "After univariate comparison and Lasso regression, hypertension, lower serum albumin, sequential organ failure assessment (SOFA) score, tidal volume, and respiratory rate were identified as independent risk factors for weaning failure." (PMID 40225039, 2025). "At its core, the investigation's focused examination of both serum uric acid and albumin levels in hypertension represents an innovative approach, distinguishing it from previous research that typically examined these parameters in isolation." (PMID 39897307, 2025). "Using univariate and multivariate logistic regression, we identified eight predictors: BMI, hypertension, chronic bronchitis, peptic ulcer history, surgical approach, anastomotic technique, postoperative albumin levels, and anastomotic location." (PMID 40956011, 2025). "During follow-up, patients who developed cognitive impairment were significantly older and had longer disease duration, lower levels of albumin, hematocrit, and blood lipids, as well as a higher prevalence of hypertension." (PMID 41487420, 2025). "Through retrospective analysis, the present study unveiled that risk factors for DGE after PPPD included anxiety state, BMI, hypertension, preoperative blood lipid levels, and albumin levels on the third day after surgery." (PMID 40988445, 2025). "The identified variables included age, alcohol consumption, hypertension, traditional open surgery, surgery time, lymphocyte count, albumin level, and prognostic nutritional index (PNI)." (PMID 40469130, 2025). "Key predictors included age, history of stroke, hypertension, triiodothyronine levels, albumin- globulin ratio, and homocysteine." (PMID 41311702, 2025). "Our findings agree with studies that demonstrate increased albumin excretion during pregnancy as both a physiological adaptation and a pathological marker of hypertensive disorders." (PMID 41181724, 2025). "At the age of 26, high blood pressure was displayed with protein sediment, asthenia, Cr 5.9 mg/dL, urea 121 mg/dL, albumin 36 g/L, and proteinuria >300 mg/dL." (PMID 40282423, 2025). "Urinary excretion of TNF‐α has been proposed as a marker of TOD in patients with essential hypertension, as it correlated with urinary albumin excretion and Cornell product, two markers of renal and heart failure, respectively." (PMID 40454610, 2025). "A previous observational study in patients with hypertension reported that urinary vanin-1 correlated positively with urinary albumin and inversely with eGFR18." (PMID 38280883, 2024). "Key predictive factors such as Albumin/Globulin ratio, gender, hypertension, homocysteine levels, Neutrophil to HDL Ratio (NHR), and history of stroke were evaluated." (PMID 39734492, 2024). "The most common AEs of lenvatinib were decreased albumin (n = 28, 54.9%), hypertension (n = 23, 45.1%), increased AST (n = 21, 41.2%), and increased TB (n = 18, 35.2%)." (PMID 39128062, 2024). "There were significant differences in hypertension, albumin, UA, C3, FA, 2hPBG, FCP between the two groups (p < 0.05), and the other factors were not statistically significant (p > 0.05)." (PMID 38887608, 2024). "Except for the prevalence of hypertension, levels of ALB, DBIL, TG, and FBG, statistically significant differences were observed among the three groups in all other baseline characteristics." (PMID 38595644, 2024). "Using LASSO regression, nine significant variables emerged as pivotal predictors in our model: Albumin to Globulin Ratio, Creatinine, Gender, Homocysteine, Hypertension, Low-Density Lipoprotein, Neutrophil to HDL Ratio, Stroke, and Total Cholesterol." (PMID 39734492, 2024).
Hypertension (continued). "Patients in the CKD progression group had a higher prevalence of hypertension (P < 0.001), lower serum albumin levels and eGFR (P < 0.001 and P < 0.001, respectively), and higher urinary PCR levels (P < 0.001)." (PMID 39516745, 2024). "We have comprehensively integrated a range of key factors: the Albumin/Globulin ratio, gender, hypertension, homocysteine levels, Neutrophil to High-Density Lipoprotein Ratio, and history of stroke." (PMID 39734492, 2024). "In this study, the main adverse reactions of HAIC combined with lenvatinib and PD-1 antibody were transaminase elevation, thrombocytopenia, albumin reduction, nausea and vomiting, leukopenia, abdominal pain, and hypertension." (PMID 38711095, 2024). "Our results indicated that cardiovascular disease and CRP log were positively correlated with MIS results, whereas age, hypertension, hemoglobin level, albumin level, phosphorus level, and BMI were negatively correlated with SGA results." (PMID 39683409, 2024). "It was found that at a cut-off point of 1.85, the sensitivity and specificity of serum albumin to predict the occurrence of hypertension in NS patients was 70% and 20% respectively." (PMID 39396026, 2024). "Cox regression of the association between neutrophil percentage to albumin ratio and all-cause mortality and CVD-cause mortality among patients with hypertension." (PMID 39087072, 2024). "A multivariate COX proportional hazards model was constructed using age, hypertension, sepsis, Ca2+, creatinine, albumin, and hemoglobin as variables." (PMID 38903514, 2024). "Subgroup analysis showed a consistent association between the TG/HDL-C ratio and TA, implying that factors such as gender, BMI, age, UPRO, ALB, hypertension and severe nephrotic syndrome had negligible effects on the link between the TG/HDL-C ratio and TA." (PMID 38327562, 2024). "The most common treatment-related AEs included decreased albumin (n = 28, 54.9%), hypertension (n = 23, 45.1%), elevated aspartate transaminase (n = 21, 41.2%) and elevated total bilirubin (n = 18, 35.2%) in TACE-LEN group." (PMID 39128062, 2024). "Hypertension, glucose, glycohemoglobin A1c, neutrophil-lymphocyte ratio and ultrasensitive C-reactive protein to albumin ratio levels were highly significant in evaluating the prognosis of patients." (PMID 38903919, 2024). "The results of this study suggest that the incidence of hypertension is lower when serum albumin is in the high stability group." (PMID 38779492, 2024). "The progressors were older (P = 0.001) and had a higher prevalence of hypertension (P < 0.001), lower albumin levels (P = 0.01), lower eGFR levels (P < 0.001), and higher uPCR levels (P < 0.001) than the non-progressors." (PMID 38649936, 2024). "In this study, adults aged 30–60 years who underwent physical examinations at Xiaotangshan Hospital in Beijing from 2009 to 2016 were enrolled to investigate the correlation between trajectories of changes in serum albumin concentrations and hypertension." (PMID 38779492, 2024). "A 4-year longitudinal study in Japan found that a reduced serum albumin concentration was an important predictor of hypertension." (PMID 38779492, 2024). "The results showed that age, gender, TC, ALB, MCV, FIB, PDW, LYM, hemoptysis, and hypertension are independent risk factors for the occurrence of APTB in bronchiectasis patients (p < 0.05)." (PMID 39582970, 2024). "Multivariate analysis showed that age, gender, TC, ALB, MCV, FIB, PDW, LYM, hemoptysis, and hypertension are independent risk factors for bronchiectasis patients with APTB (p < 0.05)." (PMID 39582970, 2024). "Compared with the control group, the hyperuricemia group exhibited high serum uric acid, the prevalence of GIL, serum albumin, the prevalence of hypertension, and low-density lipoprotein cholesterol (LDL) levels (P < 0.05)." (PMID 38548844, 2024).
Hypertension (continued). "SD rats exhibited characteristic features of CKD, including a decrease in creatinine clearance along with hypertension and increased urinary albumin excretion." (PMID 39223624, 2024). "After adjusting for age, sex, race, drinking, smoking, BMI, hypertension, Albumin, ALT, AST, Sodium, Calcium, Potassium, TC, HDL, the linear association between CDAI and DR remained statistically significant (P overall = 0.001)." (PMID 39081679, 2024). "The variables included in the model were age, hypertension, sepsis, serum calcium ion levels, creatinine levels, albumin levels, and hemoglobin levels." (PMID 38903514, 2024). "Stratification variables, namely gender, age, hypertension, ALB, BMI, and UPRO, and severe nephrotic syndrome were utilized to detect any identifiable patterns in effect sizes across these variables." (PMID 38327562, 2024). "The results showed that TBIL, age, albumin, BMI, combined hypertension, operation history, inhaled desflurane, anesthesia duration, intraoperative infusion volume and intraoperative blood loss, differences were statistically significant (P < 0.05)." (PMID 38956148, 2024). "In contrast, the serum uric acid level, the prevalence of GIL, serum albumin, the prevalence of hypertension, and LDL of the hyperuricemia group were significantly higher than those of the control group (P < 0.05)." (PMID 38548844, 2024). "In this study, our analysis of sex differences showed that the relationship between the four serum albumin concentration trajectories and hypertension varies by sex." (PMID 38779492, 2024). "These variables, specifically Albumin to Globulin Ratio, Gender, Homocysteine, Hypertension, Neutrophil to HDL Ratio, and Stroke, were integral in crafting a comprehensive predictive nomogram." (PMID 39734492, 2024). "We found a difference in terms of the number of patients with hypertension, and an expected significant difference between two groups in terms of weight, BMI, and serum albumin concentration." (PMID 39519422, 2024). "There was no statistical difference regarding age, sex, degree of proteinuria, levels of serum albumin, baseline eGFR at diagnosis, presence of hypertension at diagnosis, remission status, relapse, or number of relapses between these two groups of patients." (PMID 39693288, 2024). "The results showed that hypertension (OR = 7.272, 95% CI: 1.650–32.044, p = 0.009), albumin (OR = 1.147, 95% CI: 1.018–1.293, p = 0.024), fasting C-peptide (OR = 1.443, 95% CI: 1.066–1.955, p = 0.018) were three independent risk factors for obesity group." (PMID 38887608, 2024). "Our study successfully develops a novel predictive model for CMBs by integrating diverse clinical and laboratory parameters, including the Neutrophil to HDL Ratio, Albumin/Globulin ratio, gender, hypertension, homocysteine levels, and history of stroke." (PMID 39734492, 2024). "Lenvatinib-related AEs were hypertension, decreased albumin, fatigue, elevated AST, elevated TB, decreased PLT, decreased WBC, decreased appetite, proteinuria, diarrhea, and edema." (PMID 39128062, 2024). "In this study, it has been observed that hypertension has resulted in a notable increase in urinary albumin leak, as shown by comparing the albumin creatinine ratio during the pre-UUO period in both groups." (PMID 38338817, 2024). "Proteins angiotensinogen (AGT), albumin (ALB), APOL1, and uromodulin (UMOD) were associated with CKD and hypertension with high disease scores of 5.0 (100% confidence), 4.0 (80%), 3.9 (78%), and 3.8 (76%), respectively." (PMID 38402394, 2024). "Univariate analysis identified age, male sex, hypertension, cardiovascular disease, dyslipidemia, cerebrovascular disease, urea, creatinine, AST, total bilirubin, LDH, albumin, procalcitonin, WBC, CRP, NLR and PAR as possible risk factors for ICU admission." (PMID 36950410, 2023).